ATF3 (activating transcription factor 3)
Diseases named in the same sentence as ATF3 in open-access papers (continued):
Sharing a sentence is not in itself a finding about the gene and the disease.
hypospadias (14 papers, 2016 to 2025). Hypospadias is the displacement of the urethral meatus on the ventrum of the penis. "Hypospadias is a relatively common abnormality in children, affecting approximately 1/150 newborn males, and is associated with the MAMLD1 (Xp28) and ATF3 (1p32.3) genes for 46,XY-isolated hypospadias." (PMID 33158283, 2020). "Mutations of MAP3K1 and ATF3 were also found to be associated with an increased risk of hypospadias." (PMID 31856834, 2019). "Finally, three other deletions were found respectively in SPAG16, playing a role in the axoneme of the sperm, RYR2, whose mutations have been associated to cardiac diseases and ATF3, a candidate gene for hypospadias." (PMID 30042735, 2018). "Moreover, the TGF-β signaling pathway and its downstream genes, including activating transcription factor 3, connective tissue growth factor and cysteine-rich angiogenic inducer 61, have been suggested as potential factors in the etiology of hypospadias." (PMID 39624466, 2025). "Several genes have been founded to link with hypospadias such as DGKK, ESRs, HOX, ATF3 and VAMP." (PMID 39959693, 2025).
liver fibrosis (14 papers, 2020 to 2026). "ATF3 has been implicated in the progression of liver fibrosis, but further research is necessary to elucidate the precise regulatory pathways by which ATF3 influences fibrosis." (PMID 39358917, 2024). "To elucidate the molecular mechanism underlying rSjP40‐mediated inhibition of ATF3 in alleviating liver fibrosis, we predicted the upstream microRNAs targeting ATF3 using multiple databases, including TargetScan, miRDB and miRtarBase." (PMID 39031798, 2024). "Our identification of ATF3 as a potential KLF10 target provides valuable insights into the molecular mechanisms underlying the protective role of KLF10 against liver fibrosis." (PMID 37628783, 2023). "Surprisingly, the key role of a single transcription factor, ATF3, in determining the extent of liver fibrosis impressed us, because liver fibrosis is a complex disease associated with multiple molecules and signalings." (PMID 33311456, 2020). "Moreover, our results indicate that ATF3 is a direct target of microRNA‐494‐3p, a microRNA associated with anti‐liver fibrosis effects." (PMID 39031798, 2024). "ATF3 induces the expression of pro-fibrotic genes, suggesting that ATF3 can promote liver fibrosis by activating stellate cells." (PMID 41522362, 2026). "The chemokine CXCL14 is also involved in the ATF3/Cxcl14/Jak2 signaling axis in hepatic stellate cells responsible for liver fibrosis." (PMID 40893164, 2025). "In conclusion, this study provides a comprehensive analysis of the microRNA‐494‐3p/ATF3/α‐SMA signalling axis in rSjP40‐mediated inhibition of LX‐2 cell activation, highlighting ATF3 as a potential therapeutic target for liver fibrosis." (PMID 39031798, 2024). "Findings revealed that the specific deletion of CXCL14 in HSCs suppressed liver fibrosis in mice via the activating transcription factor 3 (ATF3)/CXCL14/RUNX1/JAK2 signalling pathway." (PMID 39358917, 2024). "ATF3 has been implicated in fibrosis, with studies showing its upregulation in the CCL4‐induced mouse liver fibrosis model." (PMID 39031798, 2024). "Taken together, these results indicate that ATF3 knockdown in liver tissue of mice significantly alleviates liver fibrosis induced by S. japonicum." (PMID 39031798, 2024). "We identified ATF3 as a potential target gene of KLF10 by RNA sequencing analysis of liver tissues from KLF10 KO mice with HSD-induced liver fibrosis." (PMID 37628783, 2023). "By RNA sequencing analysis of liver tissues from KLF10 knockout mice with severe liver fibrosis induced by a high-sucrose diet, we identified ATF3 as a potential target gene regulated by KLF10." (PMID 37628783, 2023). "Hepatic fibrosis as measured with Sirius red staining was reduced in SIRT7−/− mice with ATF3 inactivation." (PMID 36516757, 2022). "It has shown that ATF3 mRNA and protein expression were significantly increased in liver samples from patient with liver fibrosis compared to healthy liver tissues, which was consistent with the expression of α-SMA." (PMID 33311456, 2020). "Taken together, these results suggest that ATF3 depletion ameliorates the progression of liver fibrosis via inhibiting HSCs activation instead of affecting HCs function." (PMID 33311456, 2020). "All these data indicate that ATF3 aggravates liver fibrosis through promoting the expression of the pro-fibrotic genes and activation of HSCs, rather than regulating the apoptosis and proliferation in HCs." (PMID 33311456, 2020). "Taken together, these results demonstrate that TGF-β/ATF3/lnc-SCARNA10 form an axis in liver fibrosis." (PMID 33311456, 2020). "The expression pattern of ATF3 was similar in the HSCs isolated from the liver fibrosis model in the certain time points, suggesting ATF3 was an early response gene and played an important role in HSCs activation." (PMID 33311456, 2020). "In summary, we have provided, for the first time, evidence that overexpression of ATF3 results in liver fibrosis." (PMID 33311456, 2020).
liver fibrosis (continued). "Our data revealed the potential role of ATF3 that promoted HSCs activation and liver fibrosis by increasing the expression of pro-fibrotic genes." (PMID 33311456, 2020). "Both in vivo and in vitro study have revealed that silencing ATF3 reduced the expression of pro-fibrotic genes and inhibited the activation of HSCs, thus alleviating the extent of liver fibrosis, indicating a potential protective role of ATF3 knockdown." (PMID 33311456, 2020). "Therefore, this study aimed to investigate the role and regulatory mechanism of ATF3 in HSCs activation and liver fibrosis using a mouse model of S. japonicum infection and cell function experiments." (PMID 39031798, 2024). "Knockdown of ATF3 in mouse liver significantly alleviated S. japonicum‐induced liver fibrosis." (PMID 39031798, 2024). "Furthermore, silencing of ATF3 downregulated the expression of pro‐fibrotic genes and impaired the hepatic stellate cell activation, thereby improving liver fibrosis, representing a protective role of ATF3 inhibition against fibrosis." (PMID 37773702, 2023). "However, ATF3 overexpression was found in fibrotic livers and contributed to liver fibrosis by activating hepatic stellate cells." (PMID 36481938, 2022). "Our data indicated that ATF3 was crucial for HSCs activation and liver fibrosis, which may provide a potential therapeutic target against liver fibrosis." (PMID 33311456, 2020). "Taken together, our data provide a molecular mechanism implicating induced ATF3 in liver fibrosis, suggesting that ATF3 may represent a useful target in the development of therapeutic strategies for liver fibrosis." (PMID 33311456, 2020). "Interestingly, further study also demonstrated that lnc-SCARNA10 promoted the expression of ATF3 in a TGF-β/SMAD3-dependent manner, revealing a TGF-β/ATF3/lnc-SCARNA10 axis that contributed to liver fibrosis by activating HSCs." (PMID 33311456, 2020). "Therefore, we explored the role of ATF3 in liver fibrosis, the data suggest that knockdown of ATF3 alleviated liver fibrosis by inhibiting the activation of HSCs in vivo and in vitro, while ATF3 was not involved in the apoptosis or proliferation of HCs." (PMID 33311456, 2020). "Furthermore, reducing ATF3 expression ameliorated CCl4-induced liver fibrosis by inhibiting HSCs activation in vivo and the findings were confirmed in vitro." (PMID 33311456, 2020). "Having demonstrated that ATF3 was significantly upregulated in liver fibrosis, we next investigated whether increased ATF3 contributed to liver fibrosis in vivo." (PMID 33311456, 2020). "Therefore, we focused on elucidating the role of ATF3 in liver fibrosis induced by S. japonicum." (PMID 39031798, 2024). "Taken together, these results strongly suggest ATF3 may play a regulatory role in liver fibrosis." (PMID 33311456, 2020). "Building upon prior evidence that FN mitigates renal fibrosis through SMAD3/ATF3/SLC7A11 pathway inhibition, we extended these observations to hepatic fibrosis using comprehensive analyses." (PMID 40852727, 2025). "ATF3 not only plays a vital role in inducing NAFLD and type 2 diabetes mediated by oxidative stress but also can lead to liver fibrosis by activating hepatic stellate cells." (PMID 39039254, 2024). "However, the role of ATF3 in S. japonicum‐induced liver fibrosis remains unknown." (PMID 39031798, 2024). "However, the role of ATF3 in liver fibrosis caused by S. japonicum has not been investigated, and the mechanism of ATF3 in inhibiting HSCs activation by rSjP40 remain unclear." (PMID 39031798, 2024). "Regarding the specific mechanisms of the KLF10-ATF3 axis, it is important to note that our study focused on establishing the relationship between KLF10 and ATF3 in the context of liver fibrosis." (PMID 37628783, 2023). "All these data suggest the TGF-β/ATF3/lnc-SCARNA10 axis contributes to liver fibrosis by activating HSCs and represents a novel therapeutic approach against liver fibrosis." (PMID 33311456, 2020).
liver fibrosis (continued). "Since the evidence has been illustrated that lnc-SCARNA10 was involved in promoting liver fibrosis, the transcriptional promotion of lnc-SCARNA10 by ATF3 provided a novel mechanism." (PMID 33311456, 2020). "In the present study, we showed that ATF3 was upregulated in carbon tetrachloride (CCl4) and bile duct ligation (BDL)-induced mice fibrotic livers and liver tissue samples from patients with liver fibrosis." (PMID 33311456, 2020). "ATF3 is a stress-responsive protein induced by TGF-β in HSCs and has previously been shown to activate SMAD signaling, thereby promoting HSC activation and liver fibrosis." (PMID 37628783, 2023). "In addition, we have revealed that ATF3 interacted with SMAD3 to promote the transcription of pro-fibrogenic genes and TGF-β/ATF3/lnc-SCARNA10 formed a positive feedback loop, which contributed to liver fibrosis." (PMID 33311456, 2020). "In this issue of the JCI, Yan and colleagues describe an ATF3/HES1/CEBPA/OPN pathway that links hepatocyte signals to fibrogenic activation of hepatic stellate cells and may provide new perspectives on therapeutic options for MASLD-induced liver fibrosis." (PMID 38557494, 2024). "Strikingly, ATF3 mRNA and protein expression were also significantly increased when SCARNA10 was over-expressed, and decreased when SCARNA10 was knockdown in LX-2 cells, suggesting that ATF3 and SCARNA10 could form a positive feedback loop, which aggravated the liver fibrosis." (PMID 33311456, 2020). "However, the function of ATF3 has not been extensively explored in liver fibrosis." (PMID 33311456, 2020).
neuropathy (14 papers, 2009 to 2023). A disorder affecting the nervous system that manifests with pain, tingling, numbness, and/or muscle weakness. "Here, we tested ATF3 to confirm the antihyperalgesic effect of milnacipran on cisplatin-induced neuropathy." (PMID 37765187, 2023). "Analysis of the signaling pathway that triggers neuropathy highlighted the involvement of activating transcription factor 3 (ATF3) protein." (PMID 34026827, 2021). "This protection was confirmed by the modulation of neuropathy markers, such as c-Fos, nitrotyrosine, and ATF3." (PMID 32965323, 2020). "Findings from a recent animal model mimicking chronic compression neuropathies also shows small fibre injury as determined by the evaluation of cell body areas and expression of ATF3 in dorsal root ganglia neurones." (PMID 25348629, 2014). "Therefore, in the present study, we quantified ATF3 in DRG for the assessment of cisplatin-induced neuropathy." (PMID 37765187, 2023). "We hypothesized that they might engage pathways linked with neural plasticity that prevent mitochondrial dysfunction and neuropathy, so we examined mouse EAE DRGs for the expression of the plasticity-associated proteins ATF3 and pCREB59–61." (PMID 36470947, 2022). "In the current study, we investigated whether RTX neuropathy with MβC treatment affected ATF3 profiles with double labeling of ATF3(+)/PAP(+) neurons." (PMID 30578250, 2019). "However, further evidence is needed about transcriptional changes in these DRG neurones that reflect nerve injury like responses, such as the expression of ATF3, a cell injury marker in neuropathy models." (PMID 22606297, 2012). "On the other hand, paclitaxel, but not oxaliplatin, causes expression of ATF-3, a neuropathy marker, in IB4-positive and NF200-positive nerves in the DRG and also astrocyte activation and increased protein levels of inflammatory cytokines and chemokines in the spinal cord." (PMID 31666085, 2019). "Surprisingly, in our study, we observed a slight increase in ATF3 gene expression in patients with neuropathy compared with patients without neuropathy (fold = 1.41 vs. fold = 1.19)." (PMID 34640602, 2021). "This study aimed to investigate the temporal expressions of activating transcription factor-3 (ATF-3), growth-associated protein-43 (GAP-43), neuropeptide Y (NPY) and galanin in traumatic and non-traumatic rat models of neuropathies associated with NP." (PMID 25070481, 2015).
heart failure (13 papers, 2011 to 2025). Inability of the heart to pump blood at an adequate rate to meet tissue metabolic requirements. "Next, we sought to examine the tumors’ effect on cardiac fibrosis, another hallmark of cardiac remodeling and heart failure seen in the ATF3 transgenic mouse model." (PMID 37759510, 2023). "This suggests that Atf3 is necessary to promote the decline in cardiac contractility observed in FS6KD mice and that Atf3 knockout delayed heart failure progression in FS6KD mice." (PMID 40184463, 2025). "Our findings define a novel NK cell–macrophage cytokine axis that reverses cardiac dysfunction and fibrosis in pressure-overload (transverse aortic constriction) and ATF3-transgenic heart failure models." (PMID 41322654, 2025). "Up-regulation of ATF3 in cardiac fibroblasts is a compensatory mechanism for self-protection during hypertensive ventricular remodeling and heart failure." (PMID 32670070, 2020). "Li believed that ATF3 expression in cardiac fibroblast could protect against heart failure, while ATF3 knockout markedly exaggerated hypertensive ventricular remodeling." (PMID 34966780, 2021). "Recent studies have reported that ATF3 is activated during heart failure." (PMID 34468254, 2021). "However, ATF3 plays a paradoxical role in the development of heart failure." (PMID 36704356, 2022). "Our results, in combination with previous studies, indicate that ATF3 is involved in an adequate early response to stress-stimuli in heart and suggest that dysregulation of ATF3 signal transduction might contribute to maladaptive response and, therefore, to the development of heart failure." (PMID 25136830, 2014). "Previously, similar tumor-induced cardiac beneficial effects in two other heart failure models: transverse aortic constriction (TAC) and the ATF3 transgenic mouse model." (PMID 41322654, 2025). "Fibroblast-specific ATF3 protects against heart failure by repressing MAPK-p38 signaling; conversely, cardiac-specific ATF3 promotes cardiac remodeling." (PMID 39195894, 2024).
Insulin resistance (12 papers, 2011 to 2025). Increased resistance towards insulin, that is, diminished effectiveness of insulin in reducing blood glucose levels. "Moreover, Creb1 has been shown to aggravate insulin resistance by stimulating the expression of the bZiP factor ATF3 which represses Pparγ expression and inhibits adipocyte differentiation." (PMID 33912553, 2021). "In adipose tissue, ATF3 may result in insulin resistance by downregulating Glut4 and adiponectin expression." (PMID 32922364, 2020). "HFD-fed ATF3−/− mice showed increased body-fat percentage, serum triglyceride (TG) levels, glucose intolerance and insulin resistance, WAT and BAT depot weights, BAT whitening, white-adipocyte cell size, diameter and perigonadal fat-pad weight, and liver lipid deposition." (PMID 31667363, 2019). "Next, 12 weeks after intravenously injecting HFD-fed ATF3−/− mice with AAV8-ATF3, body weight, serum TG levels, glucose intolerance, and insulin resistance were lower than in ATF3−/− mice injected with AAV8-GFP." (PMID 31667363, 2019).